IHH (Indian hedgehog signaling molecule)
Description:
[Indian hedgehog protein]: Precursor of indian hedgehog, a morphogen that activates the smoothened signaling pathway, and which is essential for bone and cartilage development (By similarity). The C-terminal part of the precursor displays an autoproteolysis and a cholesterol transferase activity, resulting (1) in the cleavage of the full-length protein into two parts, indian hedgehog protein N-product and C-product and (2) covalent attachment of a cholesterol moiety to the C-terminus of the newly generated N-product (By similarity). Both autoproteolysis and a cholesterol transferase activities occur in the endoplasmic reticulum (By similarity). Following additional lipidation, N-product acts as a morphogen, while C-product is degraded in the endoplasmic reticulum (By similarity). [Indian hedgehog protein N-product]: The dually lipidated indian hedgehog protein N-product is a morphogen that activates the smoothened signaling pathway, and which is essential for bone and cartilage development (By similarity). Acts by binding to the patched receptor (PTCH1 or PTCH2), relieving smoothened (SMO) inhibition by patched, activating the smoothened signaling pathway and transcription of target genes (By similarity). In the absence of IHH, patched represses the constitutive signaling activity of SMO (By similarity). Plays a role in morphogenesis of the skeleton by coordinating growth and differentiation of the endochondral skeleton (By similarity). Positively regulates PTHLH expression during endochondral bone formation preventing chondrocyte hypertrophy (By similarity). In contrast, participates in normal chondrocyte proliferation in a PTHLH-independent pathway (By similarity). Involved in the development of retinal pigment epithelium (RPE), photoreceptors and periocular tissues (By similarity). Plays a role in hedgehog paracrine signaling. Associated with the very-low-density lipoprotein (VLDL) particles to function as a circulating morphogen for endothelial cell integrity maintenance.
Synonyms: HHG2; BDA1
Tractability: Antibody: UniProt places it where antibodies can reach, with high confidence; its Gene Ontology location is reachable by antibodies, with high confidence; UniProt predicts a signal peptide or a membrane-spanning region. PROTAC: its protein half-life has been measured.
Gene: Protein-coding gene on chromosome 2 (219,054,424 to 219,060,921, reverse strand). Ensembl gene ENSG00000163501.
Subcellular location: Endoplasmic reticulum membrane (Indian hedgehog protein); Golgi apparatus membrane; Secreted (Indian hedgehog protein N-product); Cell membrane
Pathways (Reactome):
Signal Transduction: Activation of SMO; Class B/2 (Secretin family receptors); Hedgehog 'on' state; Hedgehog ligand biogenesis; Ligand-receptor interactions; Release of Hh-Np from the secreting cell
Developmental Biology: Formation of lateral plate mesoderm
Disease: HHAT G278V doesn't palmitoylate Hh-Np
Gene expression (Transcription): RUNX2 regulates chondrocyte maturation
Gene Ontology:
Molecular function: calcium ion binding; morphogen activity; patched binding; protein binding; cholesterol-protein transferase activity; endopeptidase activity
Biological process: skeletal system development; smoothened signaling pathway; cell fate specification; chondrocyte differentiation; heart looping; negative regulation of alpha-beta T cell differentiation; negative regulation of immature T cell proliferation in thymus; negative regulation of T cell differentiation in thymus; positive regulation of alpha-beta T cell differentiation; positive regulation of T cell differentiation in thymus; positive regulation of transcription by RNA polymerase II; protein autoprocessing; regulation of gene expression; somite development; cell-cell signaling; intein-mediated protein splicing; liver regeneration; maternal process involved in female pregnancy; negative regulation of apoptotic process; positive regulation of epithelial cell proliferation; positive regulation of smoothened signaling pathway; response to estradiol; response to mechanical stimulus; system development
Cellular component: extracellular region; plasma membrane; endoplasmic reticulum membrane; Golgi membrane; extracellular matrix
Genetic constraint (gnomAD): Loss-of-function variants: 9 observed, 28.89 expected, observed/expected ratio (o/e) 0.31, 90% interval 0.19 to 0.54. The upper end of that interval is the gene's LOEUF score, 0.54, which puts it in group 2 of 6, group 1 being the genes least tolerant of losing a copy. Missense variants: 454 observed, 586.81 expected, observed/expected ratio (o/e) 0.77, 90% interval 0.72 to 0.84. Synonymous variants: 254 observed, 256.53 expected, observed/expected ratio (o/e) 0.99, 90% interval 0.89 to 1.1.
Homologues: Orthologues: macaque IHH (99% identical), chimpanzee IHH (99% identical), rabbit IHH (97% identical), dog IHH (96% identical), guinea pig IHH (95% identical), mouse Ihh (95% identical), rat Ihh (95% identical), pig IHH (93% identical), tropical clawed frog ihh (70% identical), zebrafish dhh (51% identical), Caenorhabditis elegans wrt-4 (22% identical), Caenorhabditis elegans wrt-8 (22% identical), and 16 more. Paralogues in human: SHH (64% identical), DHH (56% identical).
Diseases named in the same sentence as IHH in open-access papers:
IHH is named in the same sentence as 88 diseases in open-access papers, as found by Europe PMC text mining. Sharing a sentence is not in itself a finding about the gene and the disease. The quoted sentences say what the papers report.
brachydactyly (10 papers, 2017 to 2025). A disease characterized by the presence of brachydactyly, including syndromic and non-syndromic forms. "Mutations in IHH located in a specific region of the N-terminal active fragment cause Brachydactyly A-1 (BDA1), which is characterized by shortness of the middle phalanges of the hands and toes and a shortened stature." (PMID 37629084, 2023). "Among Hh family members, loss of sonic hedgehog (SHH) function results in pathologies as diverse as holoprosencephaly or preaxial polydactyly, whereas mutations in indian hedgehog (IHH) lead to bone growth defects (brachydactyly or acrocapitofemoral dysplasia)." (PMID 36230363, 2022). "This is the first case report of spondylocostal dysostosis and brachydactyly associated with TBX6 and IHH variants." (PMID 35846898, 2022). "For example, we identified putative enhancers of BMPR1B and IHH (both genes are associated with brachydactyly type-A, OMIM #112500), and candidate enhancers of RUNX2, a gene linked to cleidocranial dysplasia, with brachydactyly (OMIM #119600)." (PMID 35896673, 2022).
brachydactyly type A1 (10 papers, 2018 to 2025). A rare, congenital limb malformation characterized by shortened or underdeveloped middle phalanges of all digits, that are sometimes fused with the terminal phalanges. "PTCH1 has also been found to be a negative regulator of Indian hedgehog (IHH) signaling in a mouse model of Brachydactyly type A1, a cause of short stature, with impaired interaction between IHH and receptor PTCH1 contributing to the phenotype." (PMID 40577202, 2025). "Brachydactyly type A1 (BDA1) is an autosomal dominant inheritance disease caused by missense mutations of heterozygotes in IHH." (PMID 34922634, 2021). "The findings of this report will further help our understanding the phenotype-genotype correlations of IHH pathogenic variants and related disorders including brachydactyly type A1." (PMID 32209048, 2020). "Heterozygous missense mutations in IHH result in brachydactyly type A1 (BDA1; OMIM 112500), a condition characterized by the shortening of digits due to hypoplasia/aplasia of the middle phalanx." (PMID 30651074, 2019). "Mutations in human IHH underlie brachydactyly type A1 (BDA1, MIM #112500), caused by reduced chondrogenic recruitment into the digit anlage by BMP signaling in the PFR." (PMID 29771958, 2018). "Earlier studies have shown that heterozygous missense mutations in IHH gene may cause brachydactyly type A1 (BDA1), an autosomal dominant inheritance disease characterized by apparent shortness or absence of the middle phalanges of all digits." (PMID 34922634, 2021). "It was only presented in brachydactyly type A1 patients with the variants at IHH Asp100." (PMID 32209048, 2020). "Brachydactyly type A1(BDA-1) is an autosomal dominant disorder which is caused by heterozygous pathogenic variants in a specific region of the N-terminal active fragment of Indian Hedgehog (IHH)." (PMID 32209048, 2020). "The other was a rare missense variant in IHH (p.G408R; MAF = 0.30%), which is the known causative gene of acrocapitofemoral dysplasia (MIM: 607778) and brachydactyly type A1 (MIM: 112500)." (PMID 31562340, 2019). "Mutational analyses have indicated that three heterozygous missense mutations in IHH cause brachydactyly type A1 (BDA1; OMIM 112500), which features truncated or lacking phalanges." (PMID 31757091, 2019). "Homozygous mutations in Indian Hedgehog (IHH; MIM 600726) gene are responsible for causing ACFD while Brachydactyly type A1 (BDA1; MIM 112500) presenting shortened or absent middle phalanges and often accompanied by short stature, is caused by heterozygous mutations in the same gene." (PMID 40045933, 2025).
acrocapitofemoral dysplasia (7 papers, 2016 to 2025). Acrocapitofemoral dysplasia is a recently delineated skeletal dysplasia, characterized clinically by short stature of variable degrees with short limbs, brachydactyly and narrow thorax. "The diseases related to small IHH mutations are BDA1 and acrocapitofemoral dysplasia (ACFD), a rare autosomal recessive skeletal dysplasia." (PMID 40606564, 2025). "Mutations in Indian hedgehog signaling molecule (IHH), which impair the effect of functional IHH protein derived from its precursor IHH, are commonly identified in patients with BDA1 or acrocapitofemoral dysplasia (ACFD)." (PMID 40606564, 2025). "Missense mutations in IHH lead to skeletal developmental defects, such as BDA1 and acrocapitofemoral dysplasia (ACFD)." (PMID 34070546, 2021).
craniosynostosis (7 papers, 2013 to 2025). Craniosynostosis is defined as the premature fusion of one or more cranial sutures leading to secondary distortion of skull shape resulting in skull deformities with a variable presentation. "Tandem duplications near the IHH locus have previously been implicated in ectopic expression of this gene in germline pathologies such as polysyndactyly and craniosynostosis due to the creation of novel enhancer-promoter contacts." (PMID 37805627, 2023). "Changes in physiologic expression levels are sufficient to drive dramatic clinical phenotypes, such as the association of dysregulated IHH with craniosynostosis, brachydactyly, and acrocallosal syndromes." (PMID 37805627, 2023). "Klopocki and colleagues, for example, have shown that copy-number variations involving the IHH locus are associated with syndactyly and craniosynostosis." (PMID 31188878, 2019). "Several interesting examples of CNVs resulting in craniosynostosis include IHH regulatory mutations, RUNX2 duplications, and MSX2 duplications." (PMID 29845577, 2018). "That said, IHH positively regulates intramembranous osteogenesis with IHH duplications resulting in an overexpression of IHH being associated with craniosynostosis, and Ihh−/− mice exhibiting small calvarial bones with expanded sutures." (PMID 29311969, 2017). "Loss-of-function mutations in GLI3 and IHH cause craniosynostosis and reduced osteogenesis, respectively." (PMID 29311969, 2017). "IHH locus duplications are associated with syndactyly and craniosynostosis." (PMID 40045933, 2025). "Additionally, IHH gene mutations, such as additional copies of the IHH locus, are associated malformations that result in syndactyly and craniosynostosis." (PMID 23565096, 2013). "The results revealed clear differences in expression levels of genes related to bone pathologies, craniosynostosis, mechanical loading and bone-relevant signaling pathways like WNT and IHH, emphasizing the functional differences between these bones." (PMID 37378024, 2023). "We also demonstrate a location specific regulatory role for GLI3 repressor within the suture which is independent of IHH expression, as Ihh deletion does not rescue craniosynostosis exhibited by Gli3Xt−J/Xt−J mice." (PMID 29311969, 2017).
endometriosis (6 papers, 2013 to 2025). The growth of functional endometrial tissue in anatomic sites outside the uterine body. "In a histological comparison of IHH expression in endometrial biopsy samples from women with endometriosis and healthy controls, IHH expression was decreased in secretory phase endometrium from endometriosis patients." (PMID 31387263, 2019). "Consistent with our study, IHH exhibited disease‐related expression in endometriosis." (PMID 40190183, 2025). "The IHH-COUPTFII-WNT4 pathway is involved in decidualization but is disturbed in endometriosis." (PMID 37108154, 2023). "Moreover, SOX17 expression is reduced in women with endometriosis, correlating with a drop in IHH expression, which it normally regulates by binding a distal enhancer to promote endometrial receptivity in the healthy endometrium." (PMID 31387263, 2019). "Decreased IHH expression has also been described in endometriosis." (PMID 23785665, 2013). "Some decidualization-related genes are downregulated in both the endometriotic lesions and endometrium of women with endometriosis—HOXA10, forkhead box O1 (FOXO1), Indian hedgehog signaling molecule (IHH), and CCAAT/enhancer-binding protein-beta (C/EBPbeta)." (PMID 34833476, 2021). "Due to the importance of the PGR-induced IHH-COUPTFII-WNT4 pathway in regulating epithelial proliferation and decidualization during early pregnancy these molecules are of great interest in the context of P4 resistance in endometriosis." (PMID 31387263, 2019).
osteoarthritis (6 papers, 2013 to 2025). A noninflammatory degenerative joint disease occurring chiefly in older persons, characterized by degeneration of the articular cartilage, hypertrophy of bone at the margins and changes in the synovial membrane. "MiR-1 can delay the progression of osteoarthritis by inhibiting IHH and IHH regulates RUNX2 through GLI2 to stimulate osteoblast differentiation." (PMID 36766336, 2023). "PTHrP and IHH expression in articular cartilage is correlated with osteoarthritis." (PMID 24286177, 2013). "Likewise, in pathological conditions such as osteoarthritis (OA), in which articular chondrocytes develop a hypertrophic phenotype, the upregulation of Runx2 and ALP has been detected, along with Type X collagen, MMP13 and IHH and reduced Type II." (PMID 39791725, 2024).
osteosarcoma (6 papers, 2014 to 2024). A usually aggressive malignant bone-forming mesenchymal neoplasm, predominantly affecting adolescents and young adults. "It is also interesting to note that IHH is the only gene in our 13 gene signature which individually is significantly correlated with time to death in localized TARGET osteosarcoma samples." (PMID 38538763, 2024). "In the current study, we determined the levels of expression of Hedgehog pathway components (IHH, SMO, PTCH1, and GLI1) in primary human osteosarcoma specimens and examined the association with clinical characteristics and patient outcome." (PMID 24799831, 2014). "In this study of 43 high-grade human osteosarcoma samples, we detected high expression levels of the Hedgehog ligand gene, IHH, and target genes, PTCH1 and GLI1, in most samples." (PMID 24799831, 2014). "High levels of IHH found in males may suggest that ligand-dependent Hedgehog activation may contribute to abnormal cell proliferation and thus larger tumors and higher incidence of osteosarcoma in males." (PMID 24799831, 2014). "In this study of 43 osteosarcoma samples, we detected high expression levels of the Hedgehog ligand gene, IHH, and IHH target genes, PTCH1 and GLI1, in most osteosarcoma samples." (PMID 24799831, 2014). "Hedgehog signaling is of particular interest since GLI1 and IHH are both upregulated in the poor prognosis signature in patients with localized, non-metastatic osteosarcoma." (PMID 38538763, 2024). "Six of these genes are increased (MYOM2, VEGFA, MUC1, IHH, GLI1 and GRIA1) and seven are decreased (VCAM1, EGFR, GPC3, IGF2, GNG12, GNGT1 and C3) in localized patients with poor prognosis that either relapse or die due to osteosarcoma." (PMID 38538763, 2024). "Besides IHH and GLI1, GPC3, which is downregulated in our poor prognosis osteosarcoma sub-group, has been shown to inhibit Hedgehog signaling in mouse development and in vitro in NIH 3T3 cells." (PMID 38538763, 2024). "Variable expression of IHH, DHH and SHH mRNA was detected in all human osteosarcoma cell lines." (PMID 37845394, 2023). "Variable levels of IHH, SMO, PTCH1, and GLI1 expression were observed in the osteosarcoma samples." (PMID 24799831, 2014). "Based on our current data, IHH may play a more significant role specifically in the clinical outcome of patients with non-metastatic osteosarcoma." (PMID 38538763, 2024). "In addition, the IHH pathway has been found to be constitutively active in chondrosarcoma; however, the role of Hedgehog signaling in osteosarcoma has not been investigated extensively." (PMID 24799831, 2014).
breast carcinoma (5 papers, 2011 to 2018). "We have determined that breast cancer cells express elevated staining intensities for the Hh ligand IHH and the transcription factor, GLI1, indicating that the Hh pathway is activated in breast tumor cells." (PMID 22479615, 2012). "Runx2 contributes to the ability of breast cancer cells to activate osteoclasts by up-regulating the expression of Indian Hedgehog (IHH)." (PMID 22032690, 2011). "However, up regulation of IHH observed among Chinese breast cancer cohort is contradictory to our findings." (PMID 29329585, 2018). "Using immunohistochemical analyses, we assessed the expression of the Hh ligand, IHH and the transcription factor GLI1 in a tissue array comprising 75 breast cancer tissues and 9 tissues representing normal breast." (PMID 22479615, 2012). "Specifically, expression of IHH, PTCH and GLI1/2 has been determined to be correlated with enhanced proliferation in invasive breast carcinoma, node metastasis and clinical stage of breast cancer." (PMID 22479615, 2012). "We propose that in addition to IHH and OPN, Runx2 mediates stimulation of osteoclast activity by up-regulating the expression of the osteoclastogenic cytokines IL-11 and GM-CSF in metastatic breast cancer cells." (PMID 22032690, 2011).
pancreatic cancer (5 papers, 2013 to 2025). "Moreover, IHH has also been implicated in the development of cancer, including pancreatic cancer, colorectal cancer, and invasive ductal carcinoma of the breast." (PMID 39900571, 2025). "If IHH is the major driver for Hh signaling activation, neutralizing antibodies to IHH should be effective in suppressing Hh signaling in the niche as well as liver metastasis of pancreatic cancer." (PMID 30373214, 2018). "In case of pancreatic cancer, we found the expression of IHH, PTCH1 and SMO in pancreatic cancer cell line, which signified their role of hedgehog pathway activation in this type of cancer formation." (PMID 23935937, 2013). "Taken together, we found that elevated GLI1 and GLI2, but not the ligands SHH and IHH, is required for the acquired gemcitabine resistance in pancreatic cancer both in cultured cells and in mice." (PMID 30382189, 2019).